METTL24 (methyltransferase like 24)
Description:
Probable methyltransferase.
Synonyms: C6orf186; dJ71D21.2
Tractability: Antibody: UniProt places it where antibodies can reach, with high confidence; UniProt predicts a signal peptide or a membrane-spanning region; its Gene Ontology location is reachable by antibodies, with medium confidence.
Gene: Protein-coding gene on chromosome 6 (110,243,940 to 110,358,502, reverse strand). Ensembl gene ENSG00000053328.
Subcellular location: Secreted
Gene Ontology:
Cellular component: extracellular region
Genetic constraint (gnomAD): Loss-of-function variants: 27 observed, 30.05 expected, observed/expected ratio (o/e) 0.9, 90% interval 0.66 to 1.24. The upper end of that interval is the gene's LOEUF score, 1.24, which puts it in group 5 of 6, group 1 being the genes least tolerant of losing a copy. Missense variants: 312 observed, 350.96 expected, observed/expected ratio (o/e) 0.89, 90% interval 0.81 to 0.98. Synonymous variants: 101 observed, 119.97 expected, observed/expected ratio (o/e) 0.84, 90% interval 0.72 to 0.99.
Homologues: Orthologues: chimpanzee METTL24 (99% identical), macaque METTL24 (96% identical), dog METTL24 (87% identical), pig METTL24 (86% identical), mouse Mettl24 (82% identical), rat Mettl24 (82% identical), rabbit METTL24 (78% identical), guinea pig METTL24 (70% identical), tropical clawed frog mettl24 (59% identical), zebrafish mettl24 (28% identical), Caenorhabditis elegans col-50 (4% identical), Caenorhabditis elegans col-187 (3% identical), and 10 more. Paralogues in human: SCARA3 (13% identical), CTHRC1 (12% identical).
Diseases named in the same sentence as METTL24 in open-access papers:
METTL24 is named in the same sentence as 8 diseases in open-access papers, as found by Europe PMC text mining. Sharing a sentence is not in itself a finding about the gene and the disease. The quoted sentences say what the papers report.
diffuse large B-cell lymphoma (1 paper, 2021). "For deep deletion of METTL genes in individual TCGA tumor types, only METTL24 showed deep deletion rates above 5% in diffuse large B-cell lymphoma (DLBC, 10.41%), prostate cancer (PRAD, 8.38%), and uveal melanoma (UVM, 6.25%)." (PMID 34285249, 2021).
kidney cancer (1 paper, 2022). Primary or metastatic malignant neoplasm involving the kidney. "As we were focusing on kidney cancer, we confirmed METTL24 expression in KICH, KIRC, KIPR tissues and normal neighboring kidney tissues using the GEPIA database." (PMID 36311770, 2022).
renal carcinoma (1 paper, 2022). A carcinoma arising from the epithelium of the renal parenchyma or the renal pelvis. "As a result, METTL24 might be employed as a prognostic factor in renal carcinoma clinical diagnosis and treatment." (PMID 36311770, 2022). "Also, we identified METTL24 as one protecting factor for renal cancer." (PMID 36311770, 2022). "METTL24 was significantly downregulated in three renal cancer subtypes, and since KIRC accounts for more than 70% of renal malignancies, this study selected KIRC as a representative model of renal cancer for follow-up studies." (PMID 36311770, 2022).
cancer (2 papers, 2021 to 2022). A tumor composed of atypical neoplastic, often pleomorphic cells that invade other tissues. "We initially looked at the expression of METTL24 in various cancers to see if it had a role in carcinogenesis." (PMID 36311770, 2022). "To verify METTL24 expression in KIRC, we used IHC to detect METTL24 protein expression in 88 cancer samples and 85 para-cancer samples." (PMID 36311770, 2022). "Besides, we revealed that METTL24 was decreasingly expressed in cancer tissues of 17 tumors compared to normal tissues using data sets from TCGA and GTEx." (PMID 36311770, 2022). "We identified a subset of METTL genes, notably METTL1, METTL2A, METTL2B, METTL7B, NTMT1, and METTL26, with high frequencies of genomic amplification and/or up-regulation, while METTL7A and METTL24 were under-expressed, at both mRNA and/or protein levels in a spectrum of human cancers." (PMID 34285249, 2021).
tumor (2 papers, 2021 to 2022). "Taken together, several METTL genes, including METTL1, METTL2A, METTL4, EEF1AKNMT, and METTL24, had relatively higher frequencies of genetic amplification, deletion, or mutation in various tumor types, notably LUAD, BRCA, and GBM." (PMID 34285249, 2021). "We discovered that METTL24 was considerably lower expressed in tumor tissues compared to normal tissues in 15 types of tumors as analyzed using data sets from TCGA." (PMID 36311770, 2022). "In terms of tumor subtypes, METTL24 expression was significantly lower in CCB tumorous tissues than in normal tissues, but it was much greater in CCA carcinogenic tissues than in normal samples." (PMID 36311770, 2022). "The immunohistochemical assay was performed to validate METTL24 expression in our self-built Chinese cohort (n tumor = 88, n normal = 85)." (PMID 36311770, 2022). "Our findings revealed that METTL24 was more likely to be a tumor suppressor gene in KIRC tumorigenesis, and the findings suggested that METTL24’s effects on CD4+ and CD8+ T cell infiltration might be involved in its functions in tumors." (PMID 36311770, 2022). "Notably, METTL24, the gene with the most substantial genetic deletions in TCGA tumor samples, showed significant mRNA downregulation in 11 TCGA tumor types, including BRCA and COADREAD." (PMID 34285249, 2021). "In contrast, three METTLs (METTL7A, METTL24, ETFBKMT) were under-expressed (log2 FC < − 1, FDR < 0.05) in at least three of 15 TCGA tumor types compared to normal samples." (PMID 34285249, 2021). "In this study, we analyzed METTL24 expression in KIRC tissues and normal adjacent tissues using the data sets from the Cancer Genome Atlas (TCGA) and Genotype-Tissue Expression (GTEx) databases (n tumor = 523, n normal = 72) and evaluated its prognostic value for KIRC patients." (PMID 36311770, 2022).
METTL24 also shares sentences with these, for which no sentence is quoted: prostate carcinoma (1 paper); rectal cancer (1); uveal melanoma (1).